YBX1 (Y-box binding protein 1)
Diseases named in the same sentence as YBX1 in open-access papers (continued):
Sharing a sentence is not in itself a finding about the gene and the disease.
colorectal cancer (continued). "For example, in colorectal cancer, long-chain non-coding RNA POU6F2-AS1 promotes the expression of YBX1 by directly binding to it, and YBX1, in turn, binds to the promoter region of FASN to activate its transcription." (PMID 40936898, 2025). "Co-culture experiments indicate that colorectal cancer cells promote the expression of NSUN5 and YBX1 in immune cells, leading to increased m5C levels in these cells." (PMID 40370440, 2025). "In the TCGA database, we found that the YBX1 expression level increased with the NRA of rs10890208 and rs3862218 in colorectal cancer (p = 0.003 and 0.024, respectively)." (PMID 35861369, 2023). "We analyzed YBX1 and EGFR family proteins in a colorectal cancer (CRC) cohort and provide functional analyses of YBX1 in the context of EGFR–RAS–MAPK signaling." (PMID 26779809, 2016). "Chromatin immunoprecipitation using NFY-A, NFY-B or YBX1 antibodies, respectively, revealed that YBX1 preferentially regulates CCNB1 transcription in colorectal cancer cells." (PMID 21170361, 2010). "This robust subset of YBX1 targets included CCNB1, supporting the crucial role of YBX1 in proliferation control in colorectal cancer." (PMID 21170361, 2010). "To further study the role of YBX1 in controlling MEK/ERK-dependent gene expression, we analyzed endogenous promoter sequences bound to YBX1 in HCT116 colorectal cancer cells by ChIP-on-chip assay." (PMID 21170361, 2010). "In colorectal cancer, NSUN2 and YBX1 enhance ENO1 transcription via m5C RNA modification." (PMID 40843350, 2025). "In colorectal cancer, PRMT5 mediates YBX1 methylation, regulating NF-kappa B activity." (PMID 40799245, 2025). "This study identifies NSUN2 and YBX1 as the m5C “writer” and “reader” of ENO1 in colorectal cancer, culminating in a positive feedback loop involving the NSUN2/YBX1/m5C‐ENO1 signaling axis, thereby bridging the connection between metabolic reprogramming and epigenetic remodeling." (PMID 38769664, 2024). "Similarly, BEZ235 downregulates YBX1 expression by inhibiting the PI3K/mTOR pathway, thereby suppressing the malignant proliferation of colorectal cancer cells." (PMID 39727969, 2024). "Interestingly, our group recently delineated the relationship between the transcription factors YBX1, NF-κB, and PRMT5 in colorectal cancer." (PMID 33375283, 2020).
prostate carcinoma (54 papers, 2008 to 2026). A carcinoma that arises from epithelial cells of the prostate gland. "For instance, fisetin (a phenolic fruit/vegetable compound) was predicted to compete with RNA at the cold shock domain of YBX1, inhibiting in vitro and in vivo tumor growth of prostate cancer." (PMID 32585856, 2020). "Previous reports showed that androgen ablation affected the expression level of p-glycoprotein (ABCB1), Myxovirus resistanse A (MxA), and Y-box binding protein-1 (YB-1) in prostate cancer cell." (PMID 29152111, 2017). "Knockdown of YBX1 is suggested to be related to apoptosis induction in myeloid leukemic cells, renal cell carcinoma, colon cancer, medulloblastomas, glioma cells, prostate cancer, and lung adenocarcinoma." (PMID 38255791, 2024). "We and others previously identified Y-box binding protein 1 (YB-1) and metastasis associated-1 (MTA1) as proteins regulated at the translation, and not mRNA transcription level downstream of the PI3K-AKT-mTOR signaling pathway, which is frequently deregulated in human prostate cancer." (PMID 25797255, 2015). "In prostate cancer, Aurora kinase-A (AURKA) collaborates with YBX1 to promote aggressive carcinogenic phenotypes and chemoresistance." (PMID 40799245, 2025). "These metabolic stress induced TNT formation in human PC3 and LNCaP prostate cancer cell lines via the stress-induced chaperones clusterin (CLU) and YB-1 (Y-box binding protein-1) and PI3K/Akt activation." (PMID 35267518, 2022). "Furthermore, recent studies have linked the overexpression of m6A/m5C/m1A regulatory genes, including YBX1, to poor prognosis and distinct immune microenvironments in HCC and prostate cancer." (PMID 38255791, 2024). "In prostate cancer, analyzed via electrophoretic mobility shift assay and pulldown assay, YBX1 can bind to 5mC-modified androgen receptor (AR) mRNA but not the unmodified one." (PMID 38255791, 2024). "Similarly, YB-1 (Y-box binding protein-1) (in response to endoplasmic reticulum stress) and HIF-1a (produced after exposure to hypoxia-mimetics) directly binds the CLU promoter in prostate cancer cells to stably regulate CLU expression." (PMID 37685987, 2023). "Oncogenic effects of YBX1 are found in GC, bladder cancer, glioblastoma, CRC, cholangiocarcinoma, clear cell renal cell carcinoma (ccRCC), prostate cancer, epithelial ovarian cancer and cervical cancer, mainly owing to YBX1-RNA interactions that have stabilizing effects on target RNAs." (PMID 37325635, 2023).
bladder cancer (45 papers, 2011 to 2026). "Recent reports have shown that YBX1 is associated with metabolic reprogramming and promotes tumor growth by enhancing glycolysis in bladder cancer." (PMID 41507134, 2026). "Compelling reports have implicated that YBX1 is activated by integrin signaling and participates in sustained tumor growth in bladder cancer." (PMID 34758833, 2021). "Our data highlight the regulatory mechanisms of YBX1 implicated in glycolysis and provide insight into YBX1-based targeted therapy in bladder cancer." (PMID 29029484, 2017). "In this study, we for the first time demonstrated the mechanism underlying the malignant roles of YBX1 in bladder cancer." (PMID 29029484, 2017). "YBX1 regulates the expression of c-Myc and HIF1α in bladder cancer, further upregulating glycolytic enzymes to promote glycolysis, but the role of YBX1 in regulating glycolysis in kidney cancer has not been reported." (PMID 41507134, 2026). "In bladder cancer, YBX1 recognizes and binds to m5C-modified mRNA through the indole ring of W65 in its cold-shock domain (CDS), stabilizing m5C-modified mRNA, thereby regulating mRNA metabolism." (PMID 40370440, 2025). "In cisplatin-resistant bladder cancer cells, H3K18la upregulates YBX1 and YY1 expression to confer cisplatin resistance." (PMID 41310104, 2025). "Recent studies have reported that YBX1, as a m5C binding protein, plays a role in facilitating mRNA export and stabilization in bladder cancer by recognizing m5C." (PMID 38238581, 2024). "YBX1 is also involved in maintaining the stability of m5C-modified mRNAs during bladder cancer development." (PMID 38424195, 2024). "M5C methyltransferase NSUN2 and m5C binding protein YBX1 are overexpressed in bladder cancer and have poor prognosis, promoting bladder cancer development." (PMID 37170222, 2023). "For example, YBX1 has been found to be able to work with NSUN2 to stabilize HDGF mRNA to promote the progression of bladder cancer." (PMID 36792587, 2023). "For example, NSUN2‐mediated m5C modification promotes the pathogenesis of bladder cancer by enhancing the binding of YBX1 to HDGF and thereby promotes its expression." (PMID 37228185, 2023). "In bladder cancer patients, YBX1 stabilizes oncogenic HDGF (heparin binding growth factor) mRNA by targeting the m5C-modified site on its 3′-UTR." (PMID 37325635, 2023). "YBX1 binds to HDGF mRNA in an m5C-depend manner, and ELAVL1 mediates the half-life of HDGF mRNA by interacting with YBX1, promoting bladder cancer pathogenesis." (PMID 36348434, 2022). "In human bladder cancer, YBX1 recognizes and binds with m5C-modified mRNAs through an indole ring of W65 within its cold-shock domain (CDS)." (PMID 32944246, 2020). "In bladder cancer, Y-Box Binding Protein 1 (YBX1) has been identified as a an m5C “reader” and was shown to promote carcinogenesis by stabilizing Hepatoma-Derived Growth Factor (HDGF) through an interaction with Elav-Like RNA-Binding Protein 1 (ELAVL1)." (PMID 32708015, 2020). "It was reported that the overexpression of NSUN2 and YBX1 in cancer tissues promotes tumorigenesis by maintaining mRNA stability and is significantly correlated with poor prognosis in bladder cancer patients." (PMID 32944246, 2020). "Taken together, with results obtained from YBX1 knockdown and overexpression cells, we demonstrate that YBX1 plays an important role in regulating glycolysis in bladder cancer." (PMID 29029484, 2017). "Taken together, these results, as a proof of principle, provide a novel insight into the oncogenic role of YBX1 in glycolysis and suggest the potential therapeutic strategy by targeting YBX1 in bladder cancer." (PMID 29029484, 2017). "To identify the cellular functions of YBX1 in bladder cancer, we performed gene set enrichment analysis (GSEA) in TCGA cohort." (PMID 29029484, 2017). "Previous studies have shown that YBX1 is a potential prognostic factor in bladder cancer and YBX1 plays tumor-promoting effects in cancer progression." (PMID 29029484, 2017).
bladder cancer (continued). "In bladder cancer, Twist1 regulates Y-box-binding protein-1 (YB1) expression and both Twist1 and YB1 are involved in cell growth, invasion, motility, and resistance to cisplatin and doxorubicin, but not to 5-fluorouracil (5-FU)." (PMID 28099910, 2017). "And in line with previous report in bladder cancer, knockdown of YBX1 inhibited cell proliferation and promoted cell apoptosis." (PMID 29029484, 2017). "By analyzing the TCGA bladder cancer gene expression profiles, we identified that genes involved in glycolysis is significantly enriched in high-YBX1 expression group." (PMID 29029484, 2017). "Further research shows that NSUN2 and YBX1 are aberrantly elevated in bladder cancer tissues." (PMID 40370440, 2025). "Another m5C reader, YBX1, is also highly expressed in bladder cancer and is linked to a negative prognosis." (PMID 40809690, 2025). "Moreover, the concomitant expressions of YBX1 and HIF1α elevated the glycolytic capacity of bladder cancer cells." (PMID 34440660, 2021). "Moreover, two m5C reader proteins are known: the Aly/ REF export factor (ALYREF) regulating the nuclear export of modified mRNAs and the recently discovered Y-box binding protein 1 (YBX1) promoting bladder cancer by enhancing stability of target mRNAs." (PMID 32630140, 2020). "In bladder cancer, patients with high YBX1 expression had lower overall survival rates." (PMID 29029484, 2017). "To test whether Myc or HIF1α mediates the YBX1-induced glycolytic phenotype and cellular functions in bladder cancer, we introduced Myc and HIF1α to YBX1 knockdown cells." (PMID 29029484, 2017). "The mRNA and protein level of YBX1 in five bladder cancer cell lines was measured." (PMID 29029484, 2017). "Collectively, these data indicate that increased glucose utilization may contribute to the malignant potential of YBX1 in bladder cancer." (PMID 29029484, 2017). "In this study, we showed that YBX1 could promote glycolysis in bladder cancer cells by modulating Myc and HIF1α expression, which further facilitate the expression of glycolytic enzymes and ultimately contribute to tumor progression." (PMID 29029484, 2017). "At last, we determined the potential therapeutic value of targeting YBX1 in bladder cancer." (PMID 29029484, 2017). "Meanwhile, little is known about the oncogenic functions and mechanisms of YBX1 in bladder cancer." (PMID 29029484, 2017). "Alternatively, YBX1 might be an attractive therapeutic approach for bladder cancer." (PMID 29029484, 2017). "Activation of transcription factors YBX1 and YY1 enhances cisplatin resistance in bladder cancer cells." (PMID 41179284, 2025). "Similar to this, H3K18la upregulates the transcription factors Y-box binding protein 1 (YBX1) and Yin Yang 1 (YY1) in bladder cancer, promoting anlotinib resistance and ultimately cisplatin resistance." (PMID 41267990, 2025). "They demonstrated that the H3 K18 la in the promoter regions activates the transcription factors Y-box binding protein 1 (YBX1) and Yin Yang 1 (YY1), which induce DDP resistance in bladder cancer." (PMID 40264038, 2025). "In bladder cancer, H3K18la upregulates the expression of the transcription factor Yin Yang 1 (YY1) and the Y-box binding protein 1 (YBX1), promoting resistance to cisplatin." (PMID 40057816, 2025). "YBX1 targeted oncogene heparin binding growth factor (HDGF) m5C and stabilize its mRNA to promote pathogenesis of bladder cancer." (PMID 36642732, 2023). "By binding to m5C methylated sites and recruiting ELAVL1, YBX1 maintains HDGF mRNA stability and therefore exerts an oncogenic role in bladder cancer development through the activation of HDGF." (PMID 32944246, 2020). "Consistent with the result from bioinformatic analysis, we confirmed that YBX1 is able to regulate the expression level of glycolytic enzymes, glucose utilization, lactate secretion, ECAR of bladder cancer cells." (PMID 29029484, 2017).
bladder cancer (continued). "Previous reports have shown that YBX1 acts as a key molecule regulating glycolysis-related genes in triple-negative breast cancer and promotes glycolysis in bladder cancer." (PMID 41507134, 2026). "Additionally, NSUN2 collaborates with YBX1 to stabilize HDGF3 mRNA by recruiting ELAVL1 and targeting the m5C modification site in the HDGF 3′untranslated region, ultimately promoting bladder cancer progression." (PMID 40809690, 2025). "We next focused on one cancer site that is known to affect both males and females differently, where YBX1 expression was not identified to significantly affect survival in our analysis: bladder cancer." (PMID 38538658, 2024). "In bladder cancer, m5C reader YBX1 recognized NSUN2‐induced m5C modification in 3′ UTR of hepatoma‐derived growth factor (HDGF) mRNA and further maintained its stability, therefore driving the oncogenic molecular mechanism of HDGF in bladder cancer." (PMID 38721006, 2024). "Specifically, in urinary bladder cancer (UBC), YBX1 recognizes m5C-modified mRNAs through the indole ring of W65 and maintains the stability of ELAVL1, which was revealed by single-nucleotide resolution landscape analysis of messenger RNA m5C modifications and rigorous experimental investigations." (PMID 38238581, 2024). "Previous studies have demonstrated that overexpression of YBX1 could accelerate PC growth and recognize m5C modification catalyzed by NSUN2, thereby promoting pathogenesis of bladder cancer." (PMID 37393317, 2023). "The m5C recognition protein YBX1 recognizes m5C-modified mRNA through the W65 indole ring in its cold shock domain and subsequently recruits ELAV like protein 1 (ELAVL1) to stabilize heparin-binding growth factor mRNA, which ultimately promotes bladder cancer cell proliferation and metastasis." (PMID 41326692, 2026).
glioblastoma (41 papers, 2013 to 2025). The most malignant astrocytic tumor (WHO grade IV). "We found that HMGB3 and YBX1 were predicted to target 11 risk genes for glioblastoma, including RPL5 and IDH1, as shared target genes." (PMID 39363111, 2024). "Of these, IKBKE (inhibitor of nuclear factor kappa-B kinase subunit epsilon) and YBX1 (Y box binding protein 1) have been previously implicated in glioblastoma pathogenesis and metabolic targeting of virotherapy." (PMID 34045642, 2021). "In glioblastoma, YBX1 is co-expressed with six interacting proteins involved in the cell invasion network, and as a regulator of these key molecules, it participates in regulating the protein network related to tumor invasion." (PMID 40799245, 2025). "PLK1 interacts with YBX1, directly phosphorylates S174 and S176 of YBX1, promotes its nuclear translocation, and thereby inhibits apoptosis and DNA damage in glioblastoma stem cells (GSCs)." (PMID 39727969, 2024). "TheDARS1-AS1/YBX1 complex elevates the expression of the key tumorigenesis genesE2F1 andCCND1 in glioblastoma stem cell-like cells." (PMID 38899362, 2024). "RT can enhance OV replication in tumour cells by altering gene expression, for instance, by upregulating human transcription factor Y-box binding protein 1 (YB-1) in the glioblastoma cell nuclei to upregulate the replication of oncolytic AdV dl520." (PMID 37686020, 2023). "Knockdown of YBX1 in glioblastoma cell lines had pronounced effects on cell survival and knockdown of YBX1 in mice led to a reduced tumor size." (PMID 32585856, 2020). "Additionally, interaction between DARS-AS1 and YBX1 was suggested to increase radioresistance of glioblastoma cells via post-transcriptional regulation of target genes, including homologous recombination factors." (PMID 40530699, 2025). "DARS1-AS1 interacts with YBX1, promoting glioblastoma tumorigenesis and radiation resistance." (PMID 40799245, 2025). "In glioma, YBX1 may act as an important activator of the mTOR signaling pathway and mediate the YBX1/CCT4/mLST8/mTOR axis to promote the growth of glioblastomas." (PMID 38849679, 2024). "Furthermore, DARS1 Antisense RNA 1/YBX1 also contributes to the stabilization of Forkhead Box M1 mRNA, a master transcription factor responsible for governing glioblastoma (GB) stem cell self-renewal and DNA double-strand break repair." (PMID 38255791, 2024). "Interestingly, reports have shown that YBX1 is highly expressed in different cancers, such as breast cancer, glioblastomas or myelomas." (PMID 32585856, 2020). "Our previous studies also showed that YBX1 binds and promotes the stability of mRNAs such as FOXM1 in glioblastoma cells." (PMID 40819060, 2025). "For instance, YBX1 has been shown to bind to the 5′-UTR of CCT4 mRNA and promote its translation, thereby facilitating glioblastoma development through mLST8 folding and activation of the mTOR signaling pathway." (PMID 40819060, 2025). "YBX-1 is overexpressed in both subsets of pediatric glioblastoma but not in adult glioblastoma." (PMID 39062595, 2024).